EGFR (epidermal growth factor receptor)
Diseases named in the same sentence as EGFR in open-access papers (continued):
Sharing a sentence is not in itself a finding about the gene and the disease.
cancer (continued). "Recently, computational screening was conducted to identify novel dual kinase/bromodomain inhibitors from commercially available small molecules and suggested that EGFR/BET dual inhibition is potentially effective for cancer treatment." (PMID 31937753, 2020). "In this paper, we showed that EGF conjugation increased the safety and cellular uptake of TiO2 PEG NPs when used on EGFR-expressing cancer cells via their interaction with EGFR." (PMID 33003324, 2020). "Small molecular EGFR protein tyrosine kinase inhibitors (EGFR–TKIs) have become the most innovative active component in anti-cancer management." (PMID 33321953, 2020). "Previous elegant works have shown that PIC (Cet-BPD) is highly selective against cancer cells overexpressing EGFR with 20-fold less accumulation in low EGFR cells." (PMID 31898555, 2020). "Cancer patients who initially benefit from Erlotinib, a drug targeting EGFR path, eventually develop resistance to the drug." (PMID 33194732, 2020). "TriKEs targeting two activating receptors, NKp46 and CD16, on NK cells and a tumor antigen (CD19, CD20, or EGFR) on cancer cells have been generated in the laboratory." (PMID 33505304, 2020). "Mutation subclonality analyses confirmed a genetic resistance-gap in mCRCs treated with EGFR-Abs and chemotherapy, with only 13.42% of cancer cells harboring identifiable resistance drivers." (PMID 33322618, 2020). "On the contrary, the epidermal growth factor receptor (EGFR) plays a significant role in development of cancer." (PMID 32503307, 2020). "While treating cancer, epidermal growth factor receptor-tyrosine kinase inhibitor (EGFR-TKI) still faces inevitable drug resistance." (PMID 32316715, 2020). "Beyond its role as catalytic subunit of telomerase, TERT exerts several extra-telomeric functions; among these, transcriptional regulation of EGFR is of particular relevance, especially in cancer." (PMID 33553285, 2020). "In this study, we demonstrated that GA influences cancer cell viability and specifically binds to the tyrosine kinase receptor, EGFR in NSCLC cell lines." (PMID 32204508, 2020). "Taken together, these results suggest that MNTN-affibody is a promising targeted drug delivery therapy against cancers characterized by EGFR overexpression." (PMID 32194412, 2020). "Several decades ago, EGFR was identified as an attractive cancer target because a high level of expression led to oncogenesis." (PMID 32957689, 2020). "An anti-EGFRxCD16 cyclobody was successfully generated to show cytotoxicity against EGFR-positive cancer cells, able to bind simultaneously EGFR and CD16 on the cell surface." (PMID 32911608, 2020). "The resulting activation of EGFR enhances the progression of CC through its downstream oncogenes and targets involved in the proliferation and tumorigenesis of cancer." (PMID 32708604, 2020). "For instance, reports show TAM-produced ligands such as EGF signal to EGFR on cancer cells to promote cell migration." (PMID 32665556, 2020). "Multiple types of cancer have been found to exhibit over expression of EGFR, making it a candidate for targeted therapy." (PMID 33121022, 2020). "The ERBB family of tyrosine kinase receptors, including EGFR (ERBB1/HER1), ERBB2 (Neu/HER2), ERBB3 (HER3), and ERBB4 (or HER4), has largely been associated with cancer pathogenesis and epithelium-mesenchymal transition (EMT)." (PMID 32316671, 2020). "Although EGFR is the target of many anti-cancer drugs, resistance to these drugs inevitably develops (review)." (PMID 32906765, 2020). "In fact, many strategies have been attempted to treat cancer patients especially by blocking EGF/EGFR autocrine loop." (PMID 32385236, 2020). "The cancer cells were either exposed to EGFR inhibitors only or to a combination of EGFR and SOS1 inhibitors." (PMID 32897190, 2020).
cancer (continued). "PAK1 participates in almost every stage of a cancer cell and in every indispensable signal pathway, including EGFR/HER2/MAPK, Wnt/β-catenin, JNK/c-jun, NF-κB, cell cycle, apoptosis, autophagy and others, such as TGF-β and STAT5 signaling." (PMID 32863957, 2020). "The majority of conventional chemotherapeutic drugs act by killing cancer cells by inducing apoptosis or function as epidermal growth factor receptor inhibitors or antiangiogenic drugs." (PMID 33005257, 2020). "Metabolic alterations induced by EGFR signalling appear to govern at least in part the secretion and molecular composition of cancer cell EVs." (PMID 33302515, 2020). "EGFR and HER2 are examples of overexpression/gene amplification of antigen, which is a frequent event in many cancers, predominantly in cancers of epithelial origin, and is associated with poor prognosis." (PMID 32937961, 2020). "Combination therapies using EGFR inhibitors and PPARγ agonists show promising results against some urothelial tumors in vivo as well as against other cancers." (PMID 32822399, 2020). "Previous studies have investigated cross-activation of EGFR by factors in the surrounding environment is crucial factors to cancer progression." (PMID 32121107, 2020). "In particular, we focused our attention on different types of cancers that are characterized by deregulated EGFR signaling." (PMID 33202887, 2020). "In 3D co-cultures, primary NSCLC derived cells harboring EGFR mutation responded better to erlotinib treatment than KRAS mutant or KRAS/EGFR wild type (WT) cancer cells." (PMID 32434541, 2020). "It seems that CHM-04 is a potent inhibitor of EGFR with more efficiency compared to chemotherapeutic agents in suppressing cancer malignancy." (PMID 32992587, 2020). "Results of KEGG and GO pathway analysis showed that miR-1290 had a more predominant role in cancer-related pathways than miR-1246, such as proteoglycans and epidermal growth factor receptor signaling pathways." (PMID 32047539, 2020). "Erlotinib, an epidermal growth factor receptor (EGFR) inhibitor, is used for the therapy of mutated EGFR-driven cancers." (PMID 32708822, 2020). "Epidermal growth factor receptor (EGFR) is receptor tyrosine kinase, which is overexpressed in many malignant tumours (Roskoski Jr." (PMID 32577943, 2020). "Gefitinib is an EGFR inhibitor that can block the downstream signaling of EGFR in cells, thus inhibiting the development and progression of cancer." (PMID 33028804, 2020). "A characteristic feature of cancer cells is an increased number of epidermal growth factor receptors (EGFR) on the outer cell membranes and in cellular organelles." (PMID 33138194, 2020). "Epidermal growth factor receptor (EGFR) tyrosine kinase (TK) plays an indispensable role in cancer cell proliferation, survival, adhesion, migration and differentiation." (PMID 31967481, 2020). "Erlotinib inhibits the growth of cancer cells and displays anticancer activity by selectively inhibiting tyrosine kinase autophosphorylation of the EGFR of cancer cells and suppressing the activity of its downstream Ras/MAPK signaling pathway." (PMID 32260143, 2020). "We previously reported the effect of domain order on the function of a humanized bsDb targeting the epidermal growth factor receptor (EGFR) on cancer cells, and CD3 on T cells." (PMID 33255436, 2020). "Immunotoxins were coupled with specific cell-targeting proteins that can bind to CSPG4, to CD133-expressing cancer stem cells, to EGFR, or to VEGFR." (PMID 31936595, 2020). "The repolarization of TAM led to the suppression of EGFR/Akt/Erk signaling that controlled the cancer cell proliferation." (PMID 32483443, 2020).
cancer (continued). "reports gene-enrichment scores in ∼500 cancer-related genes for gefitinib-treated EGFR mutant PC-9 cells in comparison with dimethyl sulfoxide (DMSO)." (PMID 33205120, 2020). "PLAG attenuated cancer metastatic activity via modulated PAR2/EGFR transactivation by accelerating PAR2 degradation." (PMID 32121107, 2020). "In contrast, under the same culture conditions KRAS/EGFR WT or KRAS mutant cancer cells are more sensitive to cisplatin than EGFR mutant cells." (PMID 32434541, 2020). "In line with their driver roles in cancer development and progression, cancer drugs intercepting EGFR or HER2 currently outnumber therapies targeting other hubs of signal transduction." (PMID 32398965, 2020). "Small molecule tyrosine kinase inhibitors (such as gefitinib and erlotinib) and monoclonal antibodies (such as cetuximab), each with their distinct mechanisms of action, have been developed for use in targeting EGFR in a number of cancers." (PMID 33112928, 2020). "Another bispecific immunotoxin targeting IL-13R and EGFR (DTEGF13) was constructed in order to react with overexpressed receptors on cancer cells and on normal cells." (PMID 32957689, 2020). "Specific induction of apoptosis by an EGFR-specific ADC in adherent EGFR-expressing target cancer cells was analyzed using AV-SNAP-BG-647/PI staining." (PMID 33270761, 2020). "Increasing EGFR expression in oral malignancies is closely correlated with disturbance behavior, decrease apoptosis and has an effective role in cancer invasion." (PMID 33680380, 2020). "We next tested if cancer-selective PIC–Nal can improve the overall uptake of PIC in EGFR-overexpressing OVCAR-5 cells at 24 h post-incubation." (PMID 31898555, 2020). "For assessment of molecular fluorescence imaging, preclinical studies used the anti-EGFR antibody cetuximab labeled with fluorescein isothiocyanate (FITC) to image EGFR-expressing MKN45 cancer cells." (PMID 33050602, 2020). "This analysis demonstrated drastic over-expression of LINC00973 upon treatment of H-STS cancer cells with EGFR inhibitor afatinib (200-fold)." (PMID 33171937, 2020). "Cytotoxic analysis using a panel of cancer cell lines with different combinations of MET and EGFR expression show that both dual targeting ADCs are effective in killing cancer cells with IC50 values ranging from 0.4 to 1.0 nM/L." (PMID 32962738, 2020). "EGFR is activated in nearly every cancer type, and its high expression in tumors is correlated with poor patient outcome." (PMID 33112928, 2020). "This is a unique finding for FGFR1 and RGNT, as there is not typically selection pressure for loss of the remaining wildtype allele for other mutated oncogenes in human cancers of any other type (e.g. KRAS, BRAF, EGFR)." (PMID 32859279, 2020). "The EGFR/HER2 signaling network is an effective therapeutic target for HER2-positive cancers, which are known for their aggressive biological course." (PMID 32185126, 2020). "Additional studies demonstrated the efficacy of this STAT3 decoy oligonucleotide in several cancer types, and also illustrated a benefit in overcoming EGFR inhibitor resistance." (PMID 32899142, 2020). "A recent study showed that feedback regulatory loops can modulate growth factors and receptor tyrosine kinases such as EGFR to regulate cellular functions including abnormal states such as cancer." (PMID 32833992, 2020). "Doxorubicin was selected because it is a common chemotherapy agent administered to treat several types of cancers, while the EGFR antibody has both therapeutic properties and active targeting capabilities against cancer cells." (PMID 32154648, 2020). "Oncogenic activation of receptor tyrosine kinases (RTKs), such as EGFR, is common in cancer and results in abnormal signaling through downstream pathways." (PMID 32234966, 2020). "In human squamous A431 epithelial carcinoma cells, which overexpress EGFR but lack endogenous AnxA6, stable expression of AnxA6 was associated with reduced cell growth." (PMID 32784650, 2020).
cancer (continued). "The inhibition of EGFR expression strongly suppressed ZEB1 expression in primary carcinoma tumors and cell lines." (PMID 33396457, 2020). "Prominent activators of NF-κB signaling are tumor necrosis factor receptor (TNFR) family members, lipopolysaccharides (LPS) and EGFR, in fact, EGFR and NF-κB are described as co-directional activation signaling pathways in some carcinomas, such as HNCs." (PMID 32679705, 2020). "Our interaction map further revealed an additional role of DCN as an interactor of the carcinoma‐specific receptor EGFR." (PMID 33332768, 2020). "IC50 for inhibition toward EGFR activity and the growth of human carcinoma cell lines of complexes 1–4." (PMID 32411653, 2020). "EGFR (epidermal growth factor receptor) is widely recognized for its importance in cancer and has been catalogued as an oncogene." (PMID 31608105, 2019). "For example, mutations in EGFR and amplification of ErbB2 predict sensitivity to EGFR and ErbB2 targeting cancer drugs, respectively." (PMID 31536605, 2019). "EGFR contributes to cancer progression by mediating cellular proliferation, migration, adhesion and metastasis." (PMID 30530570, 2019). "Wnt and epidermal growth factor receptor (EGFR) pathways are two prominent pathways which are involved in multiple cellular functions and their aberrant regulation is a prevalent theme in cancer biology." (PMID 31649806, 2019). "Earlier reports have shown that epidermal growth factor receptor (EGFR) plays an important role in the regulation of DNA-PKcs activity in response to radiation or anti-cancer drugs that induce DNA damage." (PMID 30626422, 2019). "For instance, combinatorial treatment targeting mTOR and EGFR has been successful in other cancers, including small cell lung cancers." (PMID 30970654, 2019). "DDAs kill cancer cells that overexpress EGFR or HER24, and DDAs decrease expression of EGFR, HER2, and HER3 and reduce phosphorylation of the pro-survival kinase Akt." (PMID 31839995, 2019). "A preclinical study has shown that EGFR activation can upregulate the VEGFR signaling pathway by increasing the production of VEGF in human cancer cells." (PMID 31699150, 2019). "Remaining two genes implicated in UBC and NMIBC survival, namely EGFR and PDCD6, are both well-known cancer genes." (PMID 31681611, 2019). "Pyk2 acts as the crossroad of multiple carcinogenic signaling pathways and Pyk2 is involved in the modulation of EGFR signaling pathway, which facilitates cancer cell proliferation, survival, migration, invasion, metastasis, and chemo‐resistance." (PMID 31368612, 2019). "This distinct property of Cet-BPD offers a unique opportunity to spatiotemporally target EGFR expressing cancer cells for selective PDT." (PMID 31438568, 2019). "Cancer cells on top of Myogel responded less to EGFR and MEK inhibitors compared to cells cultured on plastic or Matrigel." (PMID 31905951, 2019). "The activated SFTPA2 not only can help signaling transduction in EGFR signaling but also can allow cancer cells to clean the pathogens through expressing Surfactant Protein A2 (SFTPA2) to survive in early stage LADC." (PMID 31217907, 2019). "Cetuximab is a chimeric monoclonal antibody binding and inhibiting EGFR thus hindering cancer cell proliferation and growth as well as invasive potential and angiogenesis thus reducing the probability of metastasis." (PMID 31366129, 2019). "Understanding the EGFR-mediated pathophysiology in cancer has led to the development of anti-EGFR agents including small-molecule inhibitors and monoclonal antibodies." (PMID 31100782, 2019). "EGFR is a potent cancer cell growth promoter, and it is usually highly expressed on the surface of cancer cells." (PMID 31717759, 2019).
cancer (continued). "Cetuximab, a chimeric (human–mouse) monoclonal antibody targeting EGFR, can inhibit cancer cell growth and induce apoptosis." (PMID 30922269, 2019). "Intriguingly, we found that integrin αvβ3 positive cancer cells were highly enriched in EGFR-resistant samples." (PMID 31316001, 2019). "It has been reported that the activation of EGFR by EGF in some cancer cell lines results in NF-κB activation." (PMID 31470515, 2019). "The subnetwork involves an interesting combination of the downregulation of the cancer gene EGFR and the amplification of a group of genes involved in T-cell receptor signaling (PTPRC, CD247, and ARPC5)." (PMID 30978274, 2019). "All chalcones showed no toxicity to HEF cells, while they were more effective with the high-level EGFR expression cancer cell lines." (PMID 30897725, 2019). "As a member of FAK family, the relationship between Pyk2 and EGFR signaling pathway requires more attention in cancer development." (PMID 31368612, 2019). "EGFR is a prevalent target in several human cancers, such as lung, breast, colorectal, thyroid, and melanoma cancer." (PMID 31058077, 2019). "Dabrafenib and vemurafenib as inhibitors of RAF can enhance the anti-cancer effects of second-generation EGFR-TKIs (lapatinib and afatinib) in colorectal cancer cells." (PMID 31527477, 2019). "Cytotoxic anti-cancer drugs have been widely used for those with LUAD acquiring EGFR-TKI resistance." (PMID 30800222, 2019). "Several of these genes play a particular role in the growth controlling EGFR-pathway, which fits well to the markedly elevated Ki67 LI in cancers with high PTPN12 expression." (PMID 31606028, 2019). "The chalcones which showed a high cytotoxic effect against the cancer cell lines were then tested for their TKI effects on recombinant (r)EGFR." (PMID 30897725, 2019). "In the classical GBM, for example, cancer cells overexpress the TF, showing an important procoagulant phenotype, hypothetically driven by the expression of the oncogenic EGFR and its mutant form EGFRvIII." (PMID 30949114, 2019). "IGFBP7 mRNA expression in cancer cells isolated from malignant pleural effusions after acquired resistance to EGFR-TKI was significantly higher than in cancer cells from treatment-naïve effusions." (PMID 30609749, 2019). "This is the first study of its kind to report such high validation accuracy and transferability over different types of cancer cell lines and EGFR inhibitors." (PMID 30621238, 2019). "The relationship between the cancer driver mutation and mutation load was examined and found that ADC patients with EGFR mutation or ALK fusion had significantly lower levels of mutation burden when compared with EGFR and ALK wild-type population." (PMID 30992440, 2019). "Since activation of EGFR/ERK signaling pathway through ERα/GPR30 was present in other cancer cells, we detected proteins of EGFR, pEGFR, ERK, and pERK by Western blotting." (PMID 31737560, 2019). "Ibr‐7 dramatically suppressed the phosphorylation of EGFR and mTORC1/S6 signaling, thus exerting its potent anti‐cancer activity against NSCLC cells." (PMID 30663221, 2019). "β-catenin activation via EGF/EGFR induction has been demonstrated in a number of studies using cancer cells." (PMID 30287279, 2019). "According to the Cancer Cell Line Encyclopedia Database, we selected out four EGFR wild-type NSCLC cell lines (A549, H460, H1299, and H358) and one normal human bronchial epithelial cell line (16HBE) for experiments." (PMID 30911072, 2019). "In this study, ultrasound-mediated cavitation of microbubbles was investigated as a mean of enhancing the delivery of a liposome designed for chemo-radionuclide therapy targeted to EGFR overexpressing cancer." (PMID 31534505, 2019). "Several approaches have been developed to target these receptors and/or the EGFR modulated effects in cancer cells." (PMID 31756933, 2019).